PTH (parathyroid hormone)
Diseases named in the same sentence as PTH in open-access papers (continued):
Sharing a sentence is not in itself a finding about the gene and the disease.
hyperparathyroidism (continued). "They posited that in clinical contexts where hyperparathyroidism is suspected yet characterized by low or normal PTH measurements, it is prudent to employ a variety of assays to evaluate PTH levels more comprehensively." (PMID 39697923, 2024). "Beta-galactosidase is a key marker of cellular senescence and a high level of serum PTH indicates a hyperparathyroidism condition, which ultimately has adverse effects on bone and the nervous system." (PMID 39224568, 2024). "The management of hyperparathyroidism (intact parathyroid hormone (iPTH) serum levels > 585 pg/mL), frequently focuses on the appropriate control of mineral and bone markers, with the decrease in serum and dietary phosphorus as two of the targets." (PMID 38396685, 2024). "Meanwhile, higher PTH levels were observed in vegans compared to omnivores, though prevalence of hyperparathyroidism was the same in all groups." (PMID 38919395, 2024). "Inactivation of CaSR in the parathyroid gland leads to stimulation of PTH release and subsequent hyperparathyroidism." (PMID 38606357, 2024). "The definitive decision regarding which PG to excise during hyperparathyroidism surgery remained contingent upon the surgeon's intraoperative assessment, informed by preoperative data and real-time intraoperative PTH measurements." (PMID 39382656, 2024). "Hyperparathyroidism, defined by increased PTH production and high blood PTH levels, can result from parathyroid abnormalities." (PMID 38591872, 2024). "While histopathology remains the reference standard, the most crucial element for the diagnosis of brown tumors is recognizing hyperparathyroidism due to extremely high levels of parathyroid hormone (PTH) and serum calcium." (PMID 39213924, 2024). "PTH blood levels and prevalence of hyperparathyroidism in vegans, lacto-ovo-vegetarians, and omnivores." (PMID 38919395, 2024). "The increased intact PTH levels in Ctns−/− mice relative to WT mice indicate mild hyperparathyroidism in Ctns−/− mice." (PMID 39210624, 2024). "From 121 patients with severe hyperparathyroidism before transplantation, only 12 (10%) remained with elevated PTH (≥771 pg/mL) at 1 year post-transplant." (PMID 38384325, 2024). "In 1,576 kidney transplant recipients (51.6 ± 14.0 years, 57.3% male), severe hyperparathyroidism characterized by pre-transplant PTH ≥771 pg/mL (>9 times the upper limit) was present in 121 patients." (PMID 38384325, 2024). "Hyperparathyroidism, characterized by excess secretion of PTH, is common and is classified as primary, secondary, or tertiary based on etiology." (PMID 38292595, 2024). "Higher parathyroid hormone levels and a higher rate of the composite endpoint of severe hyperparathyroidism and parathyroidectomy were also observed in the SS/UC group." (PMID 38820324, 2024). "A previous study on patients with hyperparathyroidism reported the normalization of parathyroid hormone and blood calcium levels following treatment with cimetidine." (PMID 38910668, 2024). "For example, hyperparathyroidism leads to calcium and phosphorus metabolism indices and connective tissue diseases such as abnormal parathyroid hormone, scleroderma, systemic lupus erythematosus and dermatomyositis." (PMID 37058037, 2023). "Hyperparathyroidism in patients with multiple endocrine neoplasia 1 is attributed to the excessive secretion of parathyroid hormone (PTH) from multiple parathyroid glands." (PMID 37341946, 2023). "A rare type of PHPT is normocalcemic hyperparathyroidism, presenting normal serum calcium levels but an elevated PTH concentration." (PMID 36902844, 2023). "Hyperparathyroidism (PTH level >65 pg/mL) was identified in 25.7% (19/74) of vitamin-D-deficient children, 9.4% (9/96) of vitamin-D-insufficient children, and none of the vitamin-D-sufficient children." (PMID 36986058, 2023).
hyperparathyroidism (continued). "Because patients with advanced CKD show hyperparathyroidism as well as elevated levels of blood phosphate and low 1,25-vitamin D, the concept of PTH hyporesponsiveness has been long considered to be a component of CKD-MBD." (PMID 36862513, 2023). "Hyperparathyroidism (SHPT) secondary to chronic kidney disease (CKD) is characterized by high serum levels of parathyroid hormone (PTH), parathyroid gland hyperplasia, high remodeling bone disease and cardiovascular disease." (PMID 35980102, 2023). "Hyperparathyroidism is characterized by an excessive secretion of parathyroid hormone (PTH) from the parathyroid glands, necessitating complete resection of the causative glands for successful treatment." (PMID 37341946, 2023). "The preoperative PTH level can predict the success of [18F]FCh-PET imaging in hyperparathyroidism, with higher lesion-to-background ratios expected in patients with high PTH, and also estimate the volume of parathyroid adenomas." (PMID 40729208, 2023). "Several nutritional indices became equivalent to those with PTH levels in the recommended range or mild hyperparathyroidism and better than those with severe hyperparathyroidism." (PMID 37484844, 2023). "Of interest, in our series, patients presented with a median of 10 non-motor symptoms but only the presence of leg restlessness had a direct correlation with higher PTH values and prevalence of hyperparathyroidism." (PMID 36873448, 2023). "And the researcher also found that 6 months after surgery in patients with severe hyperparathyroidism, parathyroid hormone levels and the patients’ resting energy expenditure were significantly reduced." (PMID 37038353, 2023). "Hyperparathyroidism is a common endocrine disorder characterized by elevated parathyroid hormone (PTH) and serum calcium levels." (PMID 36979651, 2023). "Hyperparathyroidism (HPT) is characterized by abnormally increased production of parathyroid hormone (PTH) and the resulting disordered calcium and phosphorus metabolism." (PMID 36755240, 2023). "Hyperparathyroidism (SHPT) secondary to chronic kidney disease (CKD) is characterized by high levels of parathyroid hormone (PTH), hyperplasia of the parathyroid glands and cardiovascular disease." (PMID 35980102, 2023). "Some important risk factors are age, diabetes mellitus, and excessive suppression of parathyroid hormone serum levels due to calcium overload or treatment of hyperparathyroidism with high-dose vitamin D supplementation." (PMID 37513579, 2023). "The increase in parathyroid hormone (PTH) and serum calcium represents clear signs of hyperparathyroidism along with subsequent signs and symptoms." (PMID 38027123, 2023). "Patients with penile calciphylaxis were more likely to have hyperparathyroidism and an elevated the parathyroid hormone level at the time of diagnosis compared with controls." (PMID 37861559, 2023). "Patients typically exhibit hyperparathyroidism and elevated serum calcium levels due to elevated levels of parathyroid hormone (PTH)." (PMID 37601648, 2023). "Hyperparathyroidism usually presents asymptomatically with elevated levels of calcium and parathyroid hormone; this biochemical imbalance establishes the diagnosis." (PMID 37809263, 2023). "And according to Wolf, PTH gradually declined after KT, while approximately 25–80% of recipients had hyperparathyroidism one year after KT, which was in line with our findings." (PMID 37183797, 2023). "Long-term oral therapy requires the monitoring of serum phosphate calcium, 1,25-dihydroxyvitamin D levels, and PTH, which is important to prevent hyperparathyroidism and nephrocalcinosis." (PMID 37432176, 2023). "Parathyroid adenomas (ectopic) are usually small in size and have a nonspecific appearance, but they should be suspected if the patient is affected by hyperparathyroidism (elevated serum levels of calcium and parathyroid hormone)." (PMID 37368547, 2023).
hyperparathyroidism (continued). "Systemic diseases involving increased PTH secretion, such as Hyperparathyroidism, as well as PTH deficiencies such as Hypoparathyroidism, are accompanied by a variety of neuropsychological symptoms and cognitive and affective impairments, suggesting that PTH could also exercize effects on the brain." (PMID 37240884, 2023). "Short, or daily, dosing of PTH directs osteoblasts to form new cortical bone, while constitutive PTH dosing—exhibited in hyperparathyroidism—drives catabolic osteoclast resorption." (PMID 37443778, 2023). "Patients in the pre-PTX group had a less severe degree of hyperparathyroidism compared with patients in the PTX group as indicated by lower PTH and serum calcium levels." (PMID 37484844, 2023). "Many patients with active RA exhibited biochemical features suggestive of hyperparathyroidism, despite having normal serum PTH levels." (PMID 37849009, 2023). "Intraoperative parathyroid hormone (iPTH) monitoring is standard-of-care in the surgical management of hyperparathyroidism." (PMID 38239660, 2023). "Incorporation of pathological findings and biochemical analysis—showing high PTH, high calcium and low phosphate—is needed to diagnose brown tumors in the context of longstanding hyperparathyroidism." (PMID 37286908, 2023). "We conclude that there is a major correlation in patients with hyperparathyroidism between high serum calcium level, high serum parathyroid hormone level, high serum alkaline phosphatase level, and depressive symptoms." (PMID 37425517, 2023). "It is noteworthy that hyperparathyroidism, defined as PTH > 60 pg/mL, was present in nearly 20% of patients with stage 2 CKD and appeared much earlier in CKD than other complications such as anemia, acidosis, hyperkaliemia and hyperphosphatemia." (PMID 37958263, 2023). "PTH has a putative role in nociceptive modulation, and previous evidence on hyperparathyroidism has suggested a possible interrelation with RLS." (PMID 36873448, 2023). "In patients with hyperparathyroidism, the parathyroid hormone can protect against aluminum deposition in the bone." (PMID 36190833, 2022). "In case of TIO and concomitant hyperparathyroidism, which occurred in the described case, the phosphate-lowering effect of FGF-23 was enhanced by PTH action causing high bone turnover and progressive bone loss." (PMID 35090436, 2022). "In conclusion, patients receiving maintenance hemodialysis with severe hyperparathyroidism showed deterioration of nutritional status compared to patients with moderate hyperparathyroidism and patients with PTH level in the recommended range." (PMID 36176632, 2022). "Familial hyperparathyroidism is a rare, inherited endocrine disorder characterized by abnormally elevated serum calcium due to increased parathyroid hormone levels." (PMID 36176852, 2022). "All the patients had biological hyperparathyroidism and a mean serum calcium level of 2.78 ± 0.33 mmol/L and a serum PTH level of 127.19 ± 85.05 pmol/L." (PMID 35983092, 2022). "Accordingly, mild hyperparathyroidism has been reported in patients with primary hyperaldosteronism and PTH levels in these patients decrease after adrenalectomy." (PMID 35137195, 2022). "In conclusion, patients receiving MHD with severe hyperparathyroidism had deterioration of nutritional status compared to patients with moderate hyperparathyroidism and patients with PTH level within the recommended range." (PMID 36176632, 2022). "We considered that a normalisation of the calcium level at 6 weeks was a very good indicator of cured hyperparathyroidism, mainly because the PTH level can remain high for several months despite hyperparathyroidism being cured." (PMID 35454936, 2022). "Most patients at our facility have low calcium and high parathyroid hormone, therefore, dialysate calcium is kept at 3mEq/L to prevent hyperparathyroidism." (PMID 36726901, 2022).
hyperparathyroidism (continued). "Hyperparathyroidism (serum parathyroid hormone (PTH) > 6.5 pmol/L) was initially only described in single patients." (PMID 35554666, 2022). "Cinacalcet (3-(trifluoromethyl) cinnamic acid) is a CaSR agonist that has been used clinically to reduce parathyroid hormone (PTH) release in the treatment of hyperparathyroidism." (PMID 35208112, 2022). "Hyperparathyroidism is a disease in which the parathyroid glands produce excessive parathyroid hormone (PTH) in the bloodstream." (PMID 36348829, 2022). "All five patients had been tested for hyperparathyroidism within the first few weeks of life and four had increased levels of parathyroid hormone (PTH)." (PMID 35268460, 2022). "Perfusion of cinacalcet, which is indicated for the treatment of hyperparathyroidism, also induced a decrease in PTH level from SHPT cells 1 h following treatment, which is evidence that these cells were healthy and responded to the stimuli." (PMID 35140213, 2022). "Cinacalcet HCl (cinacalcet), an allosteric modulator of CaSR that increases the sensitivity of the CaSR to extracellular calcium, suppresses PTH secretion in patients with hyperparathyroidism." (PMID 36306782, 2022). "The mainstay of the pathophysiology of hyperparathyroidism is hypersecretion of parathyroid hormone (PTH), which leads to the release of calcium from bone cells by inhibiting osteoblasts and stimulating osteoclast activity." (PMID 35414046, 2022). "There was no discernable difference in the degree of nutritional impairment between patients with moderate hyperparathyroidism and patients whose PTH levels were within the target range." (PMID 36176632, 2022). "Due to the marked elevations of calcium and PTH level, he was admitted to the hospital for further investigation and management of hyperparathyroidism." (PMID 36407056, 2022). "Normocalcemia was defined as total serum calcium levels of 8.5–10.5 mg/dL, while hyperparathyroidism was defined as when intact parathyroid hormone levels exceeded 80 pg/mL." (PMID 35710357, 2022). "Hyperparathyroidism (PTH > 65 pg/mL) was observed in 11 (50%) of these individuals, including all 3 with primary hyperparathyroidism." (PMID 35612845, 2022). "In general, primary hyperparathyroidism shows high PTH and Ca levels, but Ca levels were low in this subject, excluding the possibility of hyperparathyroidism." (PMID 35029240, 2022). "Studies have shown that hypersecretion of PTH and hyperplasia and hypertrophy of parathyroid glands are characteristic of hyperparathyroidism." (PMID 35662816, 2022). "Patients with hyperparathyroidism in this subgroup had on average lower serum calcium levels and, as expected, serum calcium was negatively correlated with PTH." (PMID 35137195, 2022). "Nevertheless, most clinicians consider a PTH level greater than two times normal (>130 pg/mL) to be consistent with persistent post-transplant hyperparathyroidism (PT-HPT) within 12 months post-transplant." (PMID 36672533, 2022). "Hyperparathyroidism (HPT) is characterized by abnormal calcium and phosphorus metabolism caused by excessive secretion of parathyroid hormone (PTH)." (PMID 36561571, 2022). "Further investigations of FGF-23 and PTH interplay should be conducted to elucidate the pathogenesis of hyperparathyroidism and tumorigenesis in some cases of TIO." (PMID 35090436, 2022). "Parathyroid hormone (PTH) and the prevalence of hyperparathyroidism (HP) based on different renal population settings, weighted." (PMID 34249998, 2021). "In conclusion, the effect of FGF23 excess on TmP/GFR is altered by PTH such that the effect is ameliorated by hypoparathyroidism and the effect is augmented by hyperparathyroidism." (PMID 33615106, 2021). "CKD patients with higher levels of plasma calcium, phosphate, and parathyroid hormone have a high risk of death because CKD often causes abnormal calcium and phosphate metabolism and hyperparathyroidism." (PMID 34685394, 2021).
hyperparathyroidism (continued). "A catabolic effect would be expected at continuously high PTH dosages, as seen in patients with hyperparathyroidism." (PMID 34440827, 2021). "In the case of a sternal neoplasm, brown tumors of hyperparathyroidism should be excluded by assessing serum parathyroid hormone and calcium levels." (PMID 34395895, 2021). "In these 3 patients, PTH levels were within the normal range (one case) or slightly above the normal range (two cases) at follow-up, probably due to the persistence of hyperparathyroidism." (PMID 33909856, 2021). "This disorder results in a higher-than-normal constitutive expression of PTH resulting in a mimic of hyperparathyroidism." (PMID 35299844, 2021). "In contrast to intermittent administration of PTH, continuously elevated serum PTH, as seen in patients suffering from hyperparathyroidism, results in reduced osteogenesis and decreased bone mass." (PMID 33953694, 2021). "Hyperparathyroidism is a metabolic disorder characterized by the excessive production of the parathyroid hormone." (PMID 33669104, 2021). "It is well documented that PTH exerts biphasic effects on skeletal homeostasis, with continuous hyperparathyroidism being catabolic, while intermittent treatment boosts bone formation." (PMID 34899374, 2021). "Hyperparathyroidism is a disease that develops as a result of excessive parathyroid hormone (PTH) secretion of the parathyroid glands." (PMID 35110094, 2021). "Only 3 studies (4%) assessed renal osteodystrophy or bone metabolism, but only by measuring parathyroid hormone or mentioning the diagnosis of hyperparathyroidism." (PMID 34386850, 2021). "The lower calcitriol concentration and the trend towards hypocalcemia due to decreased gut calcium absorption promote PTH secretion and hyperparathyroidism." (PMID 33924419, 2021). "Given that chronic kidney diseases are often accompanied by hyperparathyroidism and result in complex, combined catabolic and anabolic activities in the bones, we evaluated parathyroid hormone (PTH) levels." (PMID 33869176, 2021). "In contrast, NPT2aKO mice have decreased serum PTH levels, thus supporting a role for conditions other than hyperparathyroidism, such as hypophosphatemia, in enhancing osteocyte mediated mineral matrix resorption." (PMID 34043707, 2021). "In specific, hyperleptinemia, commonly observed in obesity, was positively correlated to PTH in both adult and pediatric individuals, indicating that stimulation of leptin—PTH axis is the initial source of hyperparathyroidism." (PMID 34422722, 2021). "Moreover, the finding that blockade of Th17 cell intestinal egress or Th17 cell influx in the BM prevented the bone loss induced by PTH provides proof of principle that pharmacological modulation of Th17 cell trafficking may represent a therapeutic strategy for hyperparathyroidism." (PMID 31980603, 2020). "Due to the high importance of hyperparathyroidism in the pathophysiology of CKD and associated calcium–phosphate complications, PTH is referred to as uremic toxin." (PMID 32823917, 2020). "Reduced calcitriol concentrations reduce the absorption of calcium and phosphate in the gastrointestinal tract and at the same time stimulate the parathyroid glands to secrete PTH, which leads to the development of hyperparathyroidism." (PMID 32823917, 2020). "Excessive secretion of PTH and prolonged exposure of bone to PTH result in the metabolic bone disorder known as hyperparathyroidism (HPT)." (PMID 32695835, 2020). "This review focuses on the gnathic metabolic bone changes that result from increased parathyroid hormone secretion in case of hyperparathyroidism." (PMID 32695835, 2020). "Previous studies with persistent hyperparathyroidism consider PTH at transplantation around 300 to 500 pg/mL, but in our series, 59% of patients in the cinacalcet group had severe hyperparathyroidism at transplant, with PTH levels ≥ 700 pg/mL." (PMID 32720971, 2020).